LAMC2 (laminin subunit gamma 2)
Diseases named in the same sentence as LAMC2 in open-access papers (continued):
Sharing a sentence is not in itself a finding about the gene and the disease.
cancer (continued). "LAMC2 is overexpressed in multiple cancers and drives tumorigenesis by interacting with α6β4 and α3β1 integrins, epidermal growth factor receptor (EGFR), and other surface receptors." (PMID 38475740, 2024). "We began our study by examining the correlation between LAMC2 and pan-cancer using The Cancer Genome Atlas (TCGA) database." (PMID 37891404, 2024). "It revealed LAMC2 gene amplification in various cancer patients among all 33 cancer types, with the highest amplification frequency (8.3%) residing in CCA patients." (PMID 38526177, 2024). "Recent investigations have analyzed that the LAMC2 is increased in multiple types of cancer and is involved in promoting the advancement of tumors." (PMID 38703300, 2024). "An in-depth investigation of the function and molecular mechanisms of LAMC2 in response to ER stress will provide new insights for cancer progression and targeted intervention." (PMID 37891404, 2024). "Results indicated that the cancer growth in the shNSUN2+Vector group was significantly slower than in the shCtrl+Vector group, while the shNSUN2+LAMC2 group partially rescued the growth of HNSCC cells in vivo." (PMID 39595099, 2024). "To examine the effect of LAMC2 on MYH9 and MYH10, we performed western blotting analyses using si-LAMC2 cancer cells, and showed that silencing LAMC2 significantly reduced the protein levels of MYH9, MYH10, as well as DRP1 and phosphorylated DRP1." (PMID 37891404, 2024). "Meanwhile, it was not only in iCCA cells but also in several non‐iCCA cancer cell lines that LAMC2 promoted EGFR translation via interacting with ≈140 kD EGFR." (PMID 38526177, 2024). "Taken together, our results revealed that in complex with MYH9 and MYH10, LAMC2 is essential for promoting ER-mitochondria interaction to alleviate ER stress and allow cancer cells to adapt and proliferate under stressful conditions." (PMID 37891404, 2024). "Transfection of cancer cells with LAMC2 resulted in the attenuation of ER stress phenotype, accompanied by elevation in mitochondrial membrane potential as well as reduction in reactive oxygen species (ROS) levels and apoptosis." (PMID 37891404, 2024). "YAP/TAZ-mediated regulation of LAMC2 has important functional consequences because we provide evidence that LM332 enables carcinoma cells to resist ferroptosis in concert with the β4 integrin." (PMID 38508310, 2024). "High expression of LAMC2 has been detected in pancreatic tumours, which modulated cancer microenvironment acidity." (PMID 37779898, 2023). "Of all the datasets investigated, LAMA3, LAMA5, LAMB3 and LAMC2 were found to be commonly upregulated in cancer when compared to adjacent tissue samples as well as in CCA tissues and cell lines." (PMID 38114514, 2023). "The results indicated that seven risk genes (SERPINE1, LAMC2, MYLK, IL21R, KRT81, MAMDC2, and PAEP) of the signature were differentially expressed in the cancer tissues compared to the normal tissues." (PMID 37636564, 2023). "LAMC2 can promote cancer progression and gemcitabine resistance through modulation of EMT and ATP-binding cassette transporters in PDAC." (PMID 36895481, 2023). "Mentioned reports prove the role of LAMC2 proteins in cancer cell migration, cellular phenotype maintenance, adhesion, migration, growth, and differentiation." (PMID 37174083, 2023). "Although LAMC2 is an important structural component of the epithelial basement membrane (BM) in various normal tissues, there is emerging evidence of a pathological role for the LAMC2 monomer in cancer." (PMID 36233212, 2022). "And the up regulation of Lamc2 detected in this study has been reported to be related to the occurrence of a variety of cancers." (PMID 35814256, 2022). "The PI3K/AKT pathway also participates in extracellular matrix remodeling and VM process through activating MMP-14 and -2, facilitating the cleavage of LAMC2, thereby promoting VM-related motility of cancer cells." (PMID 36418859, 2022).
cancer (continued). "One of these, the Laminin subunit γ-2 (LAMC2) was part of the original set of the eight ‘seed’ cancer markers used." (PMID 36140706, 2022). "LncRNA cancer susceptibility candidate 9 (CASC9) was overexpressed in ESCC, promoting ESCC metastasis through upregulating laminin subunit gamma-2 (LAMC2) expression by interacting with the cAMP-response element-binding protein (CREB)-binding protein." (PMID 35156509, 2022). "PADI4 inhibitor treatment in cancer cells downregulated four genes related to metastatic cancer phenotypes: Laminin Subunit Gamma 2 (LAMC2), C-X-C Motif Chemokine Ligand 8 (CXCL8), Niban Apoptosis Regulator 1 (FAM129A), and Pleckstrin 2 (PLEK2)." (PMID 36233212, 2022). "Spearman correlation of the 16 hypoxia genes and 151 chemo drugs in the Genomics of Drug Sensitivity in Cancer database revealed that the expression of DCBLD2, PLEC, S100A11, PLAT, PPAP2B and LAMC2 was associated with resistance to most chemotherapies." (PMID 35155430, 2022). "LAMC2 is a component of epithelial basement membrane shown to promote chemoresistance in several cancers." (PMID 35155430, 2022). "A previous study identified LAMC2 in a proteomic analysis of PDAC cancer tissues, and high circulating levels of LAMC2 have been described." (PMID 35681634, 2022). "In fact, EGFR was part of a cluster of dysregulated genes and enriched gene sets in the FIR20 cells that define the basal breast (cancer) subtype (LAMC2, TRIM29, COL17A and cytokeratin genes (KRT6, KRT7, KRT13, KRT15))." (PMID 35579852, 2022). "Here, the subunit LAMC2 has a special function that arises from its changed cleavage products in carcinoma." (PMID 36076232, 2022). "First, LAMC2 was shown to regulate cancer progression by activating the p38-MAPK signaling pathway or PI3K-Akt signaling pathway." (PMID 34612783, 2021). "LAMC2 promotes proliferation, cell migration, and invasion in cancers including colorectal and malignant metastases." (PMID 34202278, 2021). "LAMC2 encodes the γ2 chain of laminin-332 and it is an important EMT-associated gene in various human cancers." (PMID 33995623, 2021). "Our histopathological evidence has shown that COL12A1 and FN1 are expressed from stromal cells, THBS2, and VCAN from stromal and cancer cells, while ITGA2, LAMB3, and LAMC2 are expressed solely from the cancer cells." (PMID 34007003, 2021). "The effects of the M2-like phenotype have been more closely linked to cancer progression and metastasis and therefore patient prognosis with SPINK1, LAMC2, IGFBP1, and IL-23A gene expression." (PMID 34732817, 2021). "These cell line findings are corroborated by a positive (though weak) correlation of PANTR1 with VEGF-A (R = 0.19, p < 0.001) and LAMC2 in RCC cancer tissue (R = 0.13, p = 0.0028)." (PMID 32397610, 2020). "A number of gene nodes linked to drug resistance in other cancer types (including CAT, TRIM59, ANXA2, ADM, AJUBA, HSPA1A/1B, LAMC2, TRIM14, KRT8, KRT18, KRT9, CLDN1, and SMARCA2) were also down-regulated in PARPis-sensitive AsPCs." (PMID 33213473, 2020). "Previous reports had demonstrated overexpression of LAMC2 to be related to multiple types of cancer progression, migration, and invasion in humans." (PMID 32575783, 2020). "On the other hand, LAMA3 and LAMC2 were identified in the network analysis of the grade 2 carcinoma." (PMID 32640634, 2020). "In benign MECs, Notch-1 activation triggers downregulation of LAMC2 resulting in cellular responses towards cancer hallmarks, including cell migration." (PMID 31848385, 2019). "Further, they studied the knockdown of LAMC2 in cancer cells, which was found to significantly shorten nerve invasion in an animal model." (PMID 31182680, 2019). "The identified key proteins, such as SFN, LAMC2, and ITGB4, along with their associated pathways, could serve as potential biomarkers or therapeutic targets for overcoming resistance in this cancer type." (PMID 40959663, 2025).
cancer (continued). "LAMC2 (a laminin component) may contribute to cancer development by interacting with receptors on cells." (PMID 40649881, 2025). "Additionally, numerous reports indicate a correlation between elevated LAMC2 expression and adverse prognosis in cancer." (PMID 39595099, 2024). "Notably, increased expression of these hub genes correlated with advanced cancer stages and decreased patient survival, particularly LAMC2 and PLAU, suggesting their potential as prognostic biomarkers." (PMID 38707175, 2024). "Thus, our findings attributed LAMC2 to a new function in promoting EGFR translation across different cancer cell lines." (PMID 38526177, 2024). "It is suggested that the recombinant Lm-γ2 (or the miR-29 inhibition that increases LAMC2 in wounds), in a fashion similar to that of invading cancer cells, might stimulate invasion of the epidermal tongue into the wound bed." (PMID 37981221, 2024). "In light of the crucial significance of EMT in accelerating cancer cell invasion and metastasis, LAMC2 could potentially participate in the intricate molecular mechanisms of the EMT progression in GC cells." (PMID 38703300, 2024). "The identified up-regulated genes with H3K27Ac engagement included the inflammatory response genes IL1α, IL1β, and SERPINB2; the HBEGF gene that mediates cell migration and invasion; PLAU, which is regulated by AP-1 and drives cancer metastasis; and LAMC2, which is involved in the EMT process." (PMID 37511268, 2023). "In terms of mRNA expression, microtubule affinity regulating kinase 4 (MARK4) and Laminin Subunit Gamma 2 (LAMC2), with the highest dynamic weights in sample 66, may become potential high-efficiency targets for cancer treatment." (PMID 37889117, 2023). "Using a single gene analysis, LAMC2 was highly expressed in HNSC compared with other cancer types." (PMID 37415741, 2023). "LAMC2 and other family members have been found overexpressed in various cancer types." (PMID 35681634, 2022). "Stromal cells (or cancer-associated cells) included endothelial cells (PECAM1/CD31+ and MMRN1+), fibroblasts (COL6A1+, COL1A1+, THY1+, and DCN+), epithelial cells (LAMC2+, KRT5+, and KRT14+), and unassigned name cells (high heat shock proteins expression), suggesting that they were cancerous cells." (PMID 35742914, 2022). "In addition, it has been found that LAMC2 induced cancer cell invasion by interacting with specific receptors and activating signaling mediators such as FAK and AKT." (PMID 36284634, 2022). "While the mesenchymal signal in simulated bulk expression profiles predominantly reflects the presence of CAFs, our analysis also identifies specific ESGs (e.g. SNAI2, SDC1/4 and LAMC2) whose expression levels in the cancer cells are higher than or comparable to those in CAFs." (PMID 33972543, 2021). "It has been reported that LAMC2 was overexpressed in various carcinomas." (PMID 32597160, 2020). "Additionally, the elevated expression of LAMC2 in cancer cells appears to drive tumorigenesis, through its interactions with several cell-surface receptors, including ITGs and EGFRs." (PMID 31182680, 2019). "Our approach covers a broad spectrum of cancer biology, of which LAMC2, ANXA2, ADAM9, and APLP2 are the most important features of the tested diagnostic model, and their implementation in clinical settings could be further examined." (PMID 30700038, 2019). "MiR-101 inhibits cancer-associated fibroblast (CAF)-promoted VM in HCC cells through a novel regulatory network, which involves the TGF-β and SDF1-mediated VE-cadherin/MMP-2/LAMC2 signaling pathway." (PMID 31772665, 2019). "We also examined the expression of LAMA3 and LAMC2 in PTC cell lines because many studies revealed that these could play an important role in carcinogenesis of several cancers." (PMID 29426928, 2018). "LAMB3, along with LAMA1, LAMA3 and LAMC2, was enriched in pathways involved in cancer." (PMID 28904855, 2017).
cancer (continued). "LAMC2 secreted by cancer cells might also inhibit AKT signaling in the neighboring cells, leading to accumulation of regional LAMC2 proteins to promote invasion and metastasis." (PMID 28765579, 2017). "In this study, LAMC2 was upregulated in cancer tissues and confirmed previous reports." (PMID 23159910, 2012). "In addition, we examined the correlation between LAMC2 and overall survival for each cancer type." (PMID 37891404, 2024). "Published data indicate that the LAMC2‐mediated signalling network plays an important role in the progression, migration and invasion of multiple types of cancer, suggesting that it might be a potential therapeutic anticancer target for inhibiting tumourigenesis." (PMID 27704726, 2017). "We quantified co-immunofluorescence of these antigens with GPA33 and found that GPA33-negative cancer cells displayed high levels of nuclear β-catenin, indicating high WNT activity, and strong expression of the EMT marker LAMC2." (PMID 39472498, 2025). "To further investigate the impact of LAMC2 on NSUN2-induced cancer progression, we established SCC25 and HSC3 cell lines with LAMC2 knockdown." (PMID 39595099, 2024). "We identified a metastasis-related cancer cell subset EP1, which was characterized with a high expression of KRT17, LAMC2, EMP1, and PLAC8." (PMID 38818308, 2024). "Eight hub genes (MMP1, MMP7, MMP13, LAMC2, LAMB3, PLAU, COL7A1, and SPP1) were upregulated in both HNSCC and LSCC, suggesting a significant role in cancer progression." (PMID 38707175, 2024). "The expression of PTK2, USP19, LAMC2, VEGFA, EPHA2, and MMP2 varies greatly among different cancer samples and has relatively high expression." (PMID 38694917, 2024). "Previous studies have indicated that LAMC2 regulates the TGF-β signaling pathway and the integrin β1- and ZEB1-dependent pathways to promote cancer progression." (PMID 39223142, 2024). "Metastasis-related cancer cell subset EP1 was characterized by gene expression of KRT17, LAMC2, and EMP1." (PMID 38818308, 2024). "We classified the cancer cells into the five cancer subtypes as CDKN2A, SOX2, CXCL1, LAMC2, and proliferating cancer based on the top markers that are highly expressed in each cluster." (PMID 36973297, 2023). "Starting from alveolar cells, the cells transformed into pathological alveolar cells, CXCL1, LAMC2, CDKN2A, proliferating, and SOX2 cancer cells as they progressed in pseudotime." (PMID 36973297, 2023). "In contrast, ginsenoside Rg1 downregulated the mRNA expression of ARG2, MMP1, S100A4, and RAPSN, and upregulated the mRNA expression of LAMC2, DSC2, KRT6A, and FOSB, thereby enhancing the anti-cancer function of granulocytes inhibited by NA." (PMID 36817446, 2023). "Moon and coworkers suggest that LAMC2 promotes metastasis in AC, while another study demonstrated the significance of circulating LAMC2 as a prognostic marker in SCLC, especially for early stage cancer." (PMID 35681609, 2022). "Subunit gamma-1 (LAMC1) was downregulated in all four cancer types, while all other subunits showed lower expression levels in SCLC; LAMC2, LAMA5, LAMB2 in LCC; and LAMA5, LAMB2, LAMA3 in AC as well." (PMID 35681609, 2022). "Highly invasive and aggressive cancer cells overexpress MMP-14 and -2 and LAMC2, which help to form a vascular structure lined by cancer cells." (PMID 36418859, 2022). "Recent studies have reported that LAMC2 is frequently overexpressed in cancer cells, particularly that have undergone EMT in different cancer types." (PMID 36284634, 2022). "For example, upregulation of CEMIP, RRM2, LAMC2, SCD, TNS4, and PLAU in humans is prognostically unfavorable for various cancers; these genes have CR-upregulated mouse orthologs." (PMID 34202278, 2021). "It is conceivable that Zeb1 during gastrulation also regulates other targets controlling cell behavior, as shown for specific laminin (LAMC2) and integrin (ITGB4) genes in cancer cells." (PMID 23667256, 2013).
cancer (continued). "Meanwhile, other cell-cell adhesion-related molecules, such as laminins (LAMA4, LAMA5, LAMB1, LAMB2 and LAMC2) and integrins (ITGA5, ITGA5, ITGB5, ITGA11 and ITGBL1), are elevated in cancer tissues." (PMID 22905095, 2012). "Moreover, studies across various cancers identified N-cadherin, Tenascin-C, P-cadherin, NFATc, NR2F, PDPN and LAMC2 as drivers of the p-EMT state." (PMID 40764669, 2025). "On the other hand, the expression patterns of genes like SFTPB, LAMC2, KRT7 and CLIC6 varied significantly among different cancer types, suggesting that these genes may play context‐dependent roles." (PMID 39828988, 2025). "LAMC2 and CASC9 have been shown to be important biomarkers for metastasis therapy and the prognosis of ESCC, confirming the potential for HTML to play a role in cancer diagnosis and treatment." (PMID 37889117, 2023). "The overexpressed integrin α (ITGA) subfamily genes ITGA2 and ITGA3 are predicted to be involved in cancer-related pathways such as PI3K-Akt signaling pathway and FA interacting with ECM genes such as laminin (LAMB3, LAMA3, and LAMC2) and collagen (COL10A1, COL12A1)." (PMID 34262595, 2021). "The roles of LAMC2, ANXA2, ADAM9, and APLP2 in cancer biology have been documented." (PMID 30700038, 2019). "Fifteen members of cancer pathways, including FOS, TGFα, FZD8, MMP1, laminin subunit gamma 2, PTGS2, laminin subunit beta 3, ITGA2, laminin subunit alpha 3, VEGFC, WNT2B, heat shock protein 90 beta family member 1, WNT5B, FGF5 and WNT3A, were up-regulated in the MC group." (PMID 30482199, 2018). "We chose to further investigate HE4’s regulation of LAMC2 and LAMB3, since these two genes code for chains of laminin-332, a secreted heterotrimer that has been well-described to promote aggression and metastatic properties in diverse cancers." (PMID 29404274, 2017). "In cancer, combined over-expression of COL4A1 and LAMC2 can distinguish OSCC from clinically normal oral cavity/oropharynx tissues; this latter study suggests that COL4A1 over-expression may be a useful biomarker for early detection of malignancy." (PMID 21989116, 2011). "Notably, none of these pairs have been directly associated with TGFβ signaling or EMT, although many of the identified ligands (e.g., LAMC2) or receptors (e.g., CD151, COL17A1, ITGA2, ITGA3, ITGA6, ITGB1, and ITGB4) occur frequently in the context of EMT and/or cancer." (PMID 36755019, 2023). "ROC analysis of laminins in OC sets revealed that LAMA2/A4/A5, LAMB1/B2/B3, and LAMC2 could be used to differentiate between malignant tumors and non-neoplastic tissues." (PMID 34512203, 2021). "Furthermore, m5C-Bis-Seq and mRNA-Seq analyses identified LAMC2 as a potential target regulated by NSUN2 in promoting EMT in HNSCC, providing novel insights into how NSUN2 modulates the m5C landscape and facilitates cancer progression through the stabilization of LAMC2 mRNA." (PMID 39595099, 2024). "In the absence of this integrin in more de-differentiated carcinoma cells, however, YAP/TAZ is unable to activate LAMC2 transcription." (PMID 38508310, 2024).
infection (3 papers, 2016 to 2022). The state of being infected such as from the introduction of a foreign agent such as serum, vaccine, antigenic substance or organism. "Uniquely in the colon, strong downregulated interactions were driven by epithelial laminins (LAMB3 and LAMC2) and integrins, with T cells and macrophages as the main immune cell types targeted upon infection." (PMID 35501398, 2022).
adenocarcinoma (2 papers, 2012 to 2023). A common cancer characterized by the presence of malignant glandular cells. "To verify potential correlation between LAMC2 and EGFR2, we first examined protein levels of the two in adenocarcinoma 73 patient tissue samples using immunohistochemistry (IHC)." (PMID 37542131, 2023).